IL4R (interleukin 4 receptor)
Diseases named in the same sentence as IL4R in open-access papers (continued):
Sharing a sentence is not in itself a finding about the gene and the disease.
asthma (continued). "In contrast, AMG 317, another fully humanized anti–IL-4Rα MAb, did not demonstrate any clinical efficacy in patients with moderate-to-severe asthma." (PMID 26334389, 2016). "IL-4-mediated depletion of pDCs is impaired in patients with asthma compared to healthy controls, despite no measurable difference in IL-4Rα expression." (PMID 26635789, 2015). "Evidence of selection bias is absent since prevalence of asthma and IL4R SNPs is comparable between those analyzed in this study and those from the original cohort." (PMID 23286427, 2013). "It was reported that this intermediate CD14+CD16+ subset (same subset is also referred to as CD14++CD16+ or CD14highCD16+) was expanded in patients with allergies and asthma and expressed a number of M2 surface markers such as CD163, CX3CR1, IL-4R, TGF-β1 and IL-10." (PMID 24358127, 2013). "Our own data reveal that 12-13-year-old children with asthma and eczema differ regarding the interleukin-4 receptor genotype from children with asthma, but with no eczema." (PMID 22577403, 2012). "Interleukin (IL)-13, IL-4, interleukin 4 receptor (IL-4Ra), signal transducer and activator of transcription 6 (STAT6) and tumor necrosis factor-alpha (TNFα) genes are key inflammatory genes in the development of allergic diseases such as asthma." (PMID 22355322, 2012). "Except for tezepelumab (anti-TSLP), these biologics are approved for asthma with specific biomarker elevations relevant to these pathways: sensitization to a perennial aeroallergen (anti-IgE), elevated AEC [anti-IL-5, anti-IL-5 receptor (IL-5R), anti-IL-4Rα], and increased FeNO (anti-IL-4Rα)." (PMID 39586024, 2025). "Among biologics, dupilumab and tezepelumab target IL-4Rα and TSLP, respectively, and IL-4 and TSLP acted on ILC2s directly in in vivo or in vitro studies; therefore, these biologics might attenuate ILC2-mediated asthma." (PMID 37371472, 2023). "We found that treatment with anti‐IgE, anti‐IL‐5/R and anti‐IL‐4R while improving asthma outcomes, also all significantly reduced the symptoms of CRSwNP measured by SNOT‐20, supporting the “one airway concept” that assumes similar pathomechanisms in CRSwNP and asthma." (PMID 34331521, 2021). "To date, this SNP has shown associations with inflammatory and autoimmune diseases such as arthritis rheumatoid, asthma, allergic diseases and atopy, but the entire role in CKD of IL-4 and its signalling pathway through IL4R still remains unknown and further studies are needed." (PMID 22817530, 2012). "However, the effect of IL-4Rα or STAT6 on FIZZ1/YM1 protein induction in an asthma model has not yet been studied." (PMID 22014099, 2011). "Human BECs from healthy and asthma donors were cultured at the air–liquid interface (ALI) and stimulated with IL-4 and IL-13, acutely or chronically, with or without IL-4Rα mAb, followed by rhinovirus (RV) infection." (PMID 40370530, 2025). "Prior links between these proteins and asthma or atopy exist (IL1RL1 and IL1RL2, IL2RA, IL4R, and IL6R), albeit not necessarily strong evidence for a causal link." (PMID 32628676, 2020). "Before the advent of genome-wide association studies (GWAS), ADAM33, ADRB2, CD14, MS4A2 (alias FCER1B), IL13, IL4, IL4R, and TNF constituted the most replicated non-HLA candidate genes with asthma and related traits." (PMID 24039878, 2013).
atopic dermatitis (54 papers, 2009 to 2026). "Stapokibart is a humanized monoclonal antibody drug targeting the interleukin receptor subunit α (IL-4Rα), and is primarily used for the treatment of atopic dermatitis." (PMID 40959433, 2025). "Dupilumab, a fully human monoclonal antibody against IL-4Rα, has revolutionized treatment of atopic dermatitis by significantly reducing skin inflammation, pruritus, and barrier dysfunction." (PMID 41226755, 2025). "The use of dupilumab, an interleukin-4 receptor antagonist approved for atopic dermatitis (AD), in patients with concurrent AA and AD continues to raise clinical questions." (PMID 40075768, 2025). "Targeting the interleukin‐4 receptor alpha (IL‐4Rα) subunit has proven clinical efficacy in atopic dermatitis (AD)." (PMID 40344321, 2025). "Some early reports have pointed out increased weight gain in a group of patients affected with atopic dermatitis treated with monoclonal antibody against IL-4Rα." (PMID 38206766, 2024). "Dupilumab is a highly efective biologic therapy that blocks the alpha subunit of interleukin 4 receptor (IL-4Rα) and disrupts T-helper 2-mediated inflammation in atopic dermatitis (AD)." (PMID 39668908, 2024). "For instance, in a case report of dupilumab, a monoclonal antibody targeting IL-4Rα used to treat atopic dermatitis, the patient developed ischemic stroke characterized by dizziness and nausea." (PMID 39193341, 2024). "Dupilumab, an IL4R-blocking antibody, has shown clinical efficacy for atopic dermatitis (AD) treatment." (PMID 38565563, 2024). "Individuals with high IgE at baseline in several diseases show clinical benefit with anti‐IL‐4Rα (dupilumab) treatment, for example, in alopecia areata, allergic asthma, and atopic dermatitis." (PMID 37417548, 2023). "Our results suggest that IL-4Rα responsiveness on innate T cells regulates acute atopic dermatitis, while on B cells it regulates IgE." (PMID 36599893, 2023). "Ocular surface diseases, including conjunctivitis, are recognized as common comorbidities in atopic dermatitis (AD) and occur at an increased frequency in patients with AD treated with biologics targeting IL-4 receptor α (IL-4Rα) or IL-13." (PMID 36626228, 2023). "As dupilumab, a recombinant fully human IgG4 monoclonal antibody with binding specificity to human interleukin-4 receptor IL-4Rα, has become paramount in the treatment of atopic dermatitis, and its use in autoimmune bullous diseases was theorized in 2019." (PMID 35743438, 2022). "The antagonist IL-4Rα mAb (dupilumab) approved for atopic dermatitis and asthma primarily blocks the actions of IL-13 on epithelial cells, smooth muscle cells, and fibroblasts." (PMID 35604387, 2022). "For example, a human anti‐IL‐4Rα monoclonal antibody which interrupts signaling of both IL‐4 and IL‐13 has demonstrated convincing efficacy in controlling moderate‐to‐severe atopic dermatitis, allergic asthma, and nasal polyps." (PMID 34429871, 2021). "Dupilumab is an anti-interleukin-4 receptor monoclonal antibody that was recently approved for the treatment of atopic dermatitis (AD)." (PMID 32183179, 2020). "Recently, IL-4 has been shown to mediate itch by acting on its receptor, IL-4Rα, on sensory neurons, and deleting neuronal IL-4Rα effectively attenuates itch in a mouse model of atopic dermatitis." (PMID 31184997, 2019). "Recent assays have evaluated the effect of dupilumab (anti-IL-4Rα) on the host–microbe interface in atopic dermatitis (available online in clinicaltrials.gov, identifier: NCT03389893)." (PMID 31195639, 2019). "Dupilumab is a human monoclonal antibody targeting the interleukin-4 receptor (IL-4R) alpha subunit to block interleukin-4 (IL-4)/IL-13 signaling and to inhibit the inflammatory response that plays a role in the development of atopic dermatitis." (PMID 30026908, 2018).
atopic dermatitis (continued). "A recent study showed that the clinical features of experimental atopic dermatitis are driven by IL-4 and IL-13 signaling via IL-4R and highlighted that IL-4R might serve as a potent therapeutic target for the treatment of AD and other allergic diseases." (PMID 35255962, 2022). "This article reviews the recent literature on PRs associated with TNF-α, interleukin (IL)-12/23 (p40), IL-17A/the IL-17 receptor (R), IL-23 (p19), and IL-4Rα inhibitors, which are commonly used for dermatological conditions, especially atopic dermatitis (AD) and psoriasis." (PMID 35884790, 2022). "IL-4Rα antibodies are only effective in subsets of asthmatics and atopic dermatitis patients, and so a similar issue remains as to whether antibodies that block LIGHT will exert activity in those unresponsive subjects." (PMID 35604387, 2022). "As dupilumab, a recombinant fully human IgG4 monoclonal antibody with binding specificity to human interleukin-4 receptor IL-4Rα has become paramount in the treatment of atopic dermatitis, its use in autoimmune bullous diseases has been theorized and it has been used to treat patients with BP." (PMID 35743438, 2022). "In addition, IL-4R signaling could increase the CXCL1 level in a mouse model of atopic dermatitis." (PMID 40005151, 2025). "Stapokibart is a humanized monoclonal antibody targeting interleukin-4 receptor subunit alpha (IL-4Rα), primarily used for atopic dermatitis, with no prior reports of its application in BP." (PMID 41939756, 2026). "A study of dupilumab treatment in atopic dermatitis patients argues that the rare patients whose IgE levels are unchanged might be those in which IL‐4R signaling is not completely blocked." (PMID 37417548, 2023).
allergic disease (51 papers, 2006 to 2025). An immune response that occurs following re-exposure to an innocuous antigen, and that requires the presence of existing antibodies against that antigen. "In vivo, the BsAb TAVO101 × IL4R-dupi reduced all hallmark features of allergic disease, including IgE production, IL-5 and CCL17 levels, eosinophilic infiltration, and mucus hypersecretion." (PMID 41294800, 2025). "For rs1801275 (IL-4R), infants with the AA genotype and low vitamin D (<15 ng/mL) had a significantly elevated allergy risk (adjusted OR = 26.14, 95% CI: 2.56–267.11, p = 0.019)." (PMID 40927566, 2025). "We were unable to demonstrate an association of IL-4 rs2243250 and IL-4R rs1801275 with airway allergic diseases in our population." (PMID 39202464, 2024). "Several studies have reported that polymorphisms of IL-4 and/or IL-4R genes are associated with allergic diseases, diabetes, cancers, and pregnancy disorders." (PMID 33920608, 2021). "SNPs and haplotypes in genes encoding IL-4, IL-4R, and IL-13 have been shown to play a critical role in allergy and IgE production." (PMID 27566584, 2016). "Moreover, following IL-4 stimulation, Gαi1/3 associated with the intracellular domain of IL-4Rα promotes IL-4Rα endosomal trafficking and Gab1-Akt activation in BMDMs, to mediate type 2 immunity, inflammation, and allergy." (PMID 39840047, 2024). "One of the advantages of the approach we used was to highlight the SNP clusters identified by the market basket analysis also the presence of genotypes of the SNPs IL-4 rs2243250 and IL-4R rs1801275 associated with allergy, respectively, in five and two of the clusters identified." (PMID 39202464, 2024). "In particular, IL-4 rs2243250, IL-4R rs1801275, and IL-13 rs1800925 variants, affecting expression and/or functionality of the gene products were considered markers of predisposition to allergy." (PMID 39202464, 2024). "Previous study showed that The IL-4R Q576R polymorphism may involve in the development of allergy through modulating specific serum IgE levels." (PMID 36910341, 2022). "Obviously, genetic factors like special variants of the IL-4, IL-4R, and IL-13 genes may have a prominent role in development of allergy; therefore, their contribution should be carefully noticed." (PMID 35307016, 2022). "In addition, SNPs in the gene locus of IL-4Rα have been associated with allergic disease." (PMID 31269967, 2019). "This study presents evidence that IL-4R signaling can be a target for developing anti-allergy therapeutics." (PMID 40005151, 2025). "IL4R rs1801275 AA, IL13 rs20541 GG, and IL-4 rs2243250 CC genotypes synergistically amplified allergy risk under vitamin D deficiency (adjusted OR = 26.14, p = 0.019; OR = 6.51, p = 0.025; OR = 4.13, p = 0.007)." (PMID 40927566, 2025). "Both the AKT inhibitor and ERK inhibitor prevented the antigen from increasing the expression of IL-4R and hallmarks of allergic reactions." (PMID 40005151, 2025). "Dupilumab (an anti‐IL‐4Rα monoclonal antibody) has been proven to be effective in multiple allergic diseases, including both allergic asthma and AD." (PMID 40781582, 2025). "Our results provide evidence that IL-4R signaling can serve as a target for developing anti-allergy drugs." (PMID 40005151, 2025). "Taken together, our results show that understanding IL-4R-mediated allergic reactions can provide clues for the development of anti-allergy therapeutics." (PMID 40005151, 2025). "Pre-biologic BEC and FeNO concentrations were elevated in the anti-IL5/5R and anti-IL4Rα biologic groups, whereas patients who subsequently initiated anti-IgE therapy tended to have higher IgE concentrations and one or more allergies." (PMID 38711495, 2024). "Some biological agents that block Th2 response, such as anti-IL-4Rα mAb, anti-IL-5/IL-5R mAb, anti-IgE mAb, are used for patients with allergic diseases." (PMID 39483683, 2024). "•IL-4Rα signaling on B cells is required at both sensitization and effector stages of allergic disease." (PMID 33383090, 2021).
allergic disease (continued). "Dual targeting of IL-4 and IL-13 with Dupilumab, a monoclonal antibody targeting IL-4Rα, has recently entered the clinic for certain allergic diseases." (PMID 32754154, 2020). "IL-4 and IL-4Rα are involved in allergic disease, and KD patients have been reported to exhibit an atopic trend." (PMID 31269967, 2019). "Variation in human IL-4Rα has been shown to affect signal transduction and to modulate TH1/TH2 balance in the blood, as well as contributing to various allergies and to mumps virus infection susceptibility." (PMID 19527513, 2009). "First, we aimed to synthesize smIL-4 that have modulated activity to the IL-4R complex by blocking the IL-4R signaling, a modality that could be potentially used to treat allergic disease." (PMID 40561016, 2025). "Based on our findings of higher phosphorylation of STAT6, and higher expression of IL-4Rα, we selected the JAK inhibitors, ruxolitinib and tofacitinib, and the anti–IL-4Rα antibody, dupilumab, as drugs to test in vitro as they are all used clinically for treatment of allergic disease." (PMID 36884218, 2023). "In addition, IL-4/IL-4R signaling promotes B cell proliferation and stimulates immunoglobulin class-switching to IgE antibody, the major antibody in allergic reactions." (PMID 35307016, 2022). "Interestingly, sensory neuron-specific deletion of IL-4Rα reduced chronic itch, a notable symptom of allergic diseases." (PMID 34975876, 2021). "Thus, IL-4 and IL-4R might mediate allergic reactions by promoting the M2 polarization of macrophages." (PMID 40005151, 2025). "Thus, IL-4R can serve as a target for developing anti-allergy drugs." (PMID 40005151, 2025). "miRNAs that can bind to the 3′ UTR of IL-4R might be developed as anti-allergy drugs." (PMID 40005151, 2025). "Dupilumab, a monoclonal antibody targeting the interleukin-4 receptor α (IL-4Rα), blocks the signalling of both IL-4 and IL-13, key mediators of the Th2 inflammatory axis involved not only in atopic dermatitis but also in the development of other allergic diseases such as asthma." (PMID 41002407, 2025). "Since IL4R and IL13 play major roles in IgE-mediated activation for allergy, they have been studied widely in different populations since 2004 and have become a promising therapeutic target for allergic reactions in recent years." (PMID 37780578, 2023). "Strategies employing blockade of activating receptors expressed on MCs, including FcεRI, IL-4R, and thymic stromal lymphopoietin receptor (TSLPR) have shown promising clinical activity in many allergic diseases, in part by reducing MC activity." (PMID 36369358, 2022). "IL-4Rα signaling on Tregs modulates expansion and the functional stability of CD4+CD25+FoxP3+ Tregs in vivo during allergic disease." (PMID 32931477, 2020). "This resulted in a module that comprised 37 genes, several of which had key roles in allergic disease, for example IFNG and IL4R." (PMID 19216740, 2009). "The identification of more chemicals that can bind to IL-4R and/or S1PR2 might give clues for developing anti-allergy therapeutics." (PMID 40005151, 2025). "The blocking of IL-4 or downregulation of IL-4R exerted negative effects on the hallmarks of allergic reactions in vitro." (PMID 40005151, 2025). "There is an urgent need for novel IL-4Rα antagonistic Abs because a large number of patients with allergic diseases still have no treatment option." (PMID 31123339, 2019). "We found that miR-34a and IL-4R formed a negative feedback loop to regulate allergic reactions." (PMID 40005151, 2025). "However, the functional role of IL-4Rα signaling on FoxP3+ Tregs during allergic disease is not yet completely clear." (PMID 32931477, 2020). "miR-34a and IL-4R could form a negative feedback loop to regulate allergic reactions in vitro." (PMID 40005151, 2025).